SCARNA15 (small Cajal body-specific RNA 15)
Synonyms: ACA45
Gene: Small Cajal body-specific RNA gene on chromosome 15 (82,755,945 to 82,756,071, forward strand). Ensembl gene ENSG00000277864.
Gene Ontology:
Biological process: RNA processing
Cellular component: Cajal body; nucleolus
Homologues: Orthologues: chimpanzee SCARNA15 (100% identical), macaque SCARNA15 (98% identical), mouse Gm54927 (96% identical), guinea pig SCARNA15 (93% identical).
Diseases named in the same sentence as SCARNA15 in open-access papers:
SCARNA15 is named in the same sentence as 3 diseases in open-access papers, as found by Europe PMC text mining. Sharing a sentence is not in itself a finding about the gene and the disease. The quoted sentences say what the papers report.
anemia (1 paper, 2021). A reduction in the number of red blood cells, the amount of hemoglobin, and/or the volume of packed red blood cells. "Interestingly, recurrent 15q25.2 microdeletions have been associated with developmental defects, intellectual disability, anemia and other symptoms, highlighting SCARNA15 as a potential new candidate gene for these severe phenotypes." (PMID 34316713, 2021).
cancer (1 paper, 2021). A tumor composed of atypical neoplastic, often pleomorphic cells that invade other tissues. "Herein, we uncover a key role for SCARNA15 in governing central cancer-promoting splicing programs." (PMID 34316713, 2021).
SCARNA15 also shares sentences with these, for which no sentence is quoted: Intellectual disability (1 paper).